ANKRD1 (ankyrin repeat domain 1)
Diseases named in the same sentence as ANKRD1 in open-access papers (continued):
Sharing a sentence is not in itself a finding about the gene and the disease.
cardiac disease (8 papers, 2014 to 2025). "In heart diseases, such as heart failure, serum Ankrd1 can be used as a diagnostic marker, but these studies were conducted in adults." (PMID 39420247, 2024). "A number of mutations in the ANKRD1 gene have been associated with cardiac disease." (PMID 28672880, 2017). "Ankrd1 is a marker of immature CM observed during embryonic development, and also of cardiac diseases, while Sprr1a is correlated with cardioprotection in ischemic injury." (PMID 35050211, 2021). "ANKRD1 is known to modulate transcriptional regulation and is involved in the process of both heart development and heart disease." (PMID 26860204, 2016). "The association of ANKRD1 with antiapoptotic response suggests its role as myocyte survival factor during late stage heart disease, warranting further studies on ANKRD1 during end-stage heart failure." (PMID 25961010, 2015).
infection (6 papers, 2014 to 2025). The state of being infected such as from the introduction of a foreign agent such as serum, vaccine, antigenic substance or organism. "Infection of multiple HDF strains with an ANKRD1-expressing lentivirus resulted in increased ANKRD1 protein levels comparable to those found in CAFs or HDFs with AR gene silencing." (PMID 38310103, 2024). "By using HCV-like infectious particle (HCV-LP), we demonstrated that HCV single-cycle infection was drastically impaired in ANKRD1 knockdown cells." (PMID 26860204, 2016). "To verify whether ANKRD1 was involved in the viral entry, we performed HCVpp infection assay." (PMID 26860204, 2016). "By single-cycle infection assay using HCV-like infectious particle (HCV-LP), we showed that HCV propagation was drastically impaired in ANKRD1 knockdown cells." (PMID 26860204, 2016). "However, HCVpp infection level was not altered in ANKRD1 knockdown cells." (PMID 26860204, 2016).
cardiovascular diseases (4 papers, 2017 to 2024). "The comprehensive profile of Ankrd1 in cardiovascular diseases, myopathy, and its potential as a candidate prognostic and diagnostic biomarker are also discussed." (PMID 39420247, 2024). "Given the evidence of ANKRD1 linkage to human cardiovascular diseases, and its upregulation during various cardiac stress conditions, we evaluated the cardiac consequences of global ANKRD1 loss upon EAM-induced DCM utilizing global Ankrd1 KO mice." (PMID 36551326, 2022). "The current views on the actions of ANKRD1 in cardiovascular disease and its utility as a candidate cardiac biomarker with diagnostic and/or prognostic potential are also discussed." (PMID 28672880, 2017). "Moreover, genes associated with human cardiovascular diseases, such as TNNT2, LMNA/C, TBX5, MYH7, ANKRD1, and NKX2.5, were also knocked-out by TALENs in human iPSCs to build cardiovascular disease models." (PMID 37626665, 2023). "Notably, Ankrd1 levels correlate with the expression of brain natriuretic peptide (BNP), a key antihypertrophic marker in cardiovascular disease models." (PMID 39420247, 2024).
adenocarcinoma (2 papers, 2018 to 2025). A common cancer characterized by the presence of malignant glandular cells. "We established afatinib- and osimertinib-resistant adenocarcinoma cell lines showing overexpression of ankyrin repeat domain 1 (ANKRD1), which was associated with epithelial-mesenchymal transition (EMT) and anti-apoptosis." (PMID 30291293, 2018).
ANKRD1 also shares sentences with these, for which no sentence is quoted: kidney disease (4 papers); myopathy (3); ischemic cardiomyopathy (2); liver diseases (2); lung squamous cell carcinoma (2); skin cutaneous melanoma (2); spinal muscular atrophy (2); adrenocortical carcinoma (1); amyotrophic lateral sclerosis (1); Arthritis (1); bladder urothelial carcinoma (1); Central core disease (1); cervical cancer (1); cholangiocarcinoma (1); Clear Cell Renal Cell Carcinoma (1); colorectal (1); congenital long-QT syndrome (1); congenital myopathies (1); crescentic glomerulonephritis (1); cyst (1); diabetic nephropathy (1); diffuse large B-cell lymphoma (1); ganglioneuroblastoma (1); glaucoma (1); glioblastoma multiforme (1); glomerulonephritis (1); head and neck squamous cell carcinoma (1); infarction (1); injury (1); keloid (1).
A further 17 diseases each share a sentence with ANKRD1 in 1 paper.